GABRE (gamma-aminobutyric acid type A receptor subunit epsilon)
Description:
Epsilon subunit of the heteropentameric ligand-gated chloride channel gated by gamma-aminobutyric acid (GABA), a major inhibitory neurotransmitter in the brain. GABA-gated chloride channels, also named GABA(A) receptors (GABAAR), consist of five subunits arranged around a central pore and contain GABA active binding site(s) located at the alpha and beta subunit interfaces (By similarity). When activated by GABA, GABAARs selectively allow the flow of chloride anions across the cell membrane down their electrochemical gradient (By similarity). GABAARs containing epsilon subunits also permit spontaneous chloride channel activity while preserving the structural information required for GABA-gated openings. GABARs containing epsilon subunit may regulate cardiac function (Probable).
Tractability: Small molecule: an approved drug acts on it; a high-quality ligand is known; it belongs to a druggable protein family. Antibody: UniProt places it where antibodies can reach, with medium confidence; UniProt predicts a signal peptide or a membrane-spanning region; its Gene Ontology location is reachable by antibodies, with medium confidence.
Gene: Protein-coding gene on chromosome X (151,953,124 to 151,974,680, reverse strand). Ensembl gene ENSG00000102287.
Subcellular location: Cell membrane; Postsynaptic cell membrane
Gene Ontology:
Molecular function: GABA-A receptor activity; GABA-gated chloride ion channel activity; extracellular ligand-gated monoatomic ion channel activity; monoatomic ion channel activity; transmembrane signaling receptor activity; transmitter-gated monoatomic ion channel activity
Biological process: negative regulation of chloride transport; chloride transmembrane transport; inhibitory synapse assembly; synaptic transmission, GABAergic; chloride transport; monoatomic ion transmembrane transport; monoatomic ion transport
Cellular component: GABA-A receptor complex; dendrite membrane; plasma membrane; postsynapse; membrane; postsynaptic membrane
Homologues: Orthologues: chimpanzee GABRE (99% identical), macaque GABRE (98% identical), rabbit GABRE (85% identical), dog GABRE (75% identical), pig GABRE (70% identical), mouse Gabre (69% identical), rat Gabre (69% identical), guinea pig GABRE (68% identical). Paralogues in human: GABRG3 (42% identical), GABRG2 (39% identical), GABRG1 (39% identical), GABRA4 (33% identical), GABRA6 (32% identical), GABRA1 (31% identical), GABRA3 (31% identical), GABRA2 (31% identical), GABRA5 (31% identical), GLRA2 (27% identical), GLRA3 (26% identical), GABRB1 (26% identical), and 33 more.
Diseases named in the same sentence as GABRE in open-access papers:
GABRE is named in the same sentence as 49 diseases in open-access papers, as found by Europe PMC text mining. Sharing a sentence is not in itself a finding about the gene and the disease. The quoted sentences say what the papers report.
breast carcinoma (7 papers, 2017 to 2025). "These genes, including NBPF12, CCDC9B, and GABRE (which encodes a subunit of the GABA receptor), are known to play roles in breast cancer progression." (PMID 41285961, 2025). "In human breast cancer, bromodomain adjacent to zinc finger domain 2A (BAZ2A) and gamma-aminobutyric acid type A receptor subunit epsilon (GABRE) have been recognized as potential therapeutic targets." (PMID 38951817, 2024). "We found that the seven GABAA receptor subunits were upregulated in TNBC breast cancers, including GABRA1, GABRA5, GABRD, GABRE, GABRP, GABRQ, and GABRG3." (PMID 36923530, 2023). "In breast cancer patient datasets (TCGA, Cell 2015 and METABRIC), expression of ABAT was negatively correlated while expression of GABRE was positively correlated with ALDH1A3 expression, consistent with the MDA-MB-231 data." (PMID 34989902, 2022).
epilepsy (5 papers, 2014 to 2024). A brain disorder characterized by episodes of abnormally increased neuronal discharge resulting in transient episodes of sensory or motor neurological dysfunction, or psychic dysfunction. "Finally, recent work with patients has shown that decreased GABRE expression correlates with cognitive impairment in schizophrenia, while variants of the GABRE gene are associated with epilepsy." (PMID 39684772, 2024). "We postulate that the GABRE gene is a likely candidate gene for epilepsies of different forms and severities." (PMID 32588540, 2020). "Our clinical and molecular genetic findings suggest that GABRE is a likely candidate gene for epilepsy." (PMID 32588540, 2020).
migraine (5 papers, 2008 to 2021). "It has been proposed that the GABRE SNP designated as rs1139916 affects the binding of extracellular ligands, and it has been associated with migraine risk in women, with carriers of variant alleles being at decreased risk." (PMID 29445327, 2018). "This study unravels, for the first time, the gene-gene interactions between NRXN2, GABRE - a GABAA-receptor - and CASK, importantly it shows the synergetic effect between those genes and its relation with migraine susceptibility." (PMID 34126933, 2021). "We for the first time show that the genetic interaction and synergetic effect between variants in NRXN2, GABRE and CASK, affects migraine predisposition." (PMID 34126933, 2021). "We analyzed the distribution of allelic, genotypic and haplotypic frequencies of twenty-three SNPs localized in the GABRE, GABRA3 and GABRQ genes to explore the role of these genes in migraine susceptibility using a case-control approach." (PMID 24040174, 2013). "Three markers located within 15 kb of the coding region of the GABRE gene and a marker in the GABRQ gene were analyzed for association with migraine in a large population (275 migraineurs versus 275 healthy individuals) of Australia Caucasians." (PMID 19087248, 2008). "Therefore, we aimed to further investigate the role and interaction of NRXN2, SYT1, GABRE and CASK, additional components involved in the control mechanisms of neurotransmitter release apparatus in migraine susceptibility." (PMID 34126933, 2021). "The synonymous GABRE 5 marker distribution for allelic and genotype frequencies did not present significant association for migraine (χ2 = 0.57, P = 0.45 and χ2 = 0.95, P = 0.62 respectively for allelic and genotype frequencies)." (PMID 19087248, 2008). "Prior linkage studies have reported mapping of a migraine gene to chromosome Xq 24–28, a region containing a cluster of genes for GABA A receptors (GABRE, GABRA3, GABRQ), which are potential candidate genes for migraine." (PMID 19087248, 2008). "In this study, we have focused on the subunit GABA A receptors type ε (GABRE) and type θ (GABRQ) genes and their involvement in migraine." (PMID 19087248, 2008). "Although this study has not implicated tested markers in the GABRE gene, further investigation of other GABA related genes, particularly in the cluster of GABA A receptor subunit genes residing at Xq 24–28 region, is required to define their potential role in migraine." (PMID 19087248, 2008).
prostate carcinoma (5 papers, 2007 to 2019). A carcinoma that arises from epithelial cells of the prostate gland. "In contrast, GABRE~miR-452~miR-224 locus is downregulated and hypermethylated in prostate cancer, suggesting tumor-suppressive role in prostate cancer." (PMID 30785618, 2018). "Meanwhile, intronic miR-224/452 cluster showed significant co-expression with their host gene GABRE in prostate cancer (R = 0.58, 0.63; FDR = 0, 0)." (PMID 30785618, 2018). "Further studies are required to establish any relationships between prostate cancer progression and increased expression levels of PTGDR, GPR15, and GABRE genes." (PMID 17553164, 2007). "In this study, we show that prostate cancer-specific hypermethylation of the eight genes AOX1, CCDC181 (C1orf114), GABRE, GAS6, HAPLN3, KLF8, MOB3B, and SLC18A2 can be detected by qMSP with very high sensitivity and specificity in scarce prostate needle biopsy samples taken at the time of diagnosis." (PMID 28084441, 2017).
melanoma (3 papers, 2019). A malignant, usually aggressive tumor composed of atypical, neoplastic melanocytes. "The transcription factor E2F1 is crucial for melanoma progression through directly transactivating the GABRE gene that expresses miR-224/miR-452." (PMID 32010624, 2019). "Transcription factor E2F1 induces the expression of GABRE (epsilon subunit of gamma-aminobutyric acid A receptor), and the miR-224/miR-452 cluster located within the intron of GABRE is involved in an EMT (epithelial–mesenchymal transition)-like process in melanoma cells." (PMID 30866509, 2019).
hepatocellular carcinoma (2 papers, 2015 to 2019). A malignant tumor that arises from hepatocytes. "Recently, NF-κB/p65 was reported to bind regulatory region of miR-224 within intron 6 of host gene GABRE promoting transcription of miR-224 in hepatocellular carcinoma." (PMID 26307684, 2015). "Moreover, positive relationships between GABRE and miR-224 levels were reported in hepatocellular carcinoma." (PMID 31810268, 2019).
infantile spasms (2 papers, 2017 to 2020). A rare epilepsy syndrome characterized by onset of epileptic spasms in infants between 2 and 12 months of age, and rarely up to 24 months. "In family S23, an 8-year-old boy with infantile spasms is homozygotes for a variant of c.1355 G>T (p.Arg452Leu) in GABRE gene that is inherited from healthy parents." (PMID 28074849, 2017).
mental disorder (2 papers, 2020 to 2021). A disease that has its basis in the disruption of mental process. "Although the enrichment does not reach significance following multiple hypothesis testing comparison, it is worth noting that additional genes are implicated in psychiatric disorders (GABRE, GNRH1, FMO1, FLG, SELE, NQO2)." (PMID 33169669, 2020).
breast tumors (1 paper, 2022). "We further confirmed the association of ABAT or GABRE expression with high ALDH1A3 in two independent datasets of primary breast tumors that later developed distal metastasis (GSE2034 and GSE12276)." (PMID 34989902, 2022). "In both patient groups, low ABAT expression in the primary breast tumor was significantly and strongly associated with increased risk of brain metastasis, while GABRE was not." (PMID 34989902, 2022). "Furthermore, when primary breast tumors had low ABAT expression, there was a higher risk for lung-specific metastasis and all distal sites excluding brain, but GABRE expression did not impact the risk of distant metastasis." (PMID 34989902, 2022).
colon adenocarcinoma (1 paper, 2022). "Ling Yan and colleagues showed that overexpression of GABRA2, GABRA3, GABRB3, GABRG2, GABRG3, GABRD, and GABRE might be diagnostic for colon adenocarcinoma." (PMID 35565356, 2022).
colon cancer (1 paper, 2024). "However, irrespective of whether expression of GABAA or GABAB receptor subunits were altered in colon cancer, expression of particular receptor subtypes (GABRA1, GABRA5, GABRD, GABRE, GABRG1, GABRG3, GABBR1, and GABBR2) was significantly associated with poor clinical outcome." (PMID 38886975, 2024).
developmental delay (1 paper, 2020). "We also collected three patients with GABRE‐variants showing milder epileptic phenotypes as well as developmental delay and intellectual disability." (PMID 32588540, 2020).
Epileptic encephalopathy (1 paper, 2020). A condition in which epileptiform abnormalities are believed to contribute to the progressive disturbance in cerebral function. "In the patients described herein, we observed that sequence variants in the GABRE gene may cause a broad range of epileptic phenotypes, from an early‐onset and severe pharmaco‐resistant epileptic encephalopathy to late‐onset and mild forms of generalized and focal epilepsy." (PMID 32588540, 2020).
leukaemia (1 paper, 2017). "Information, which has been found in the course of literature research, coincides to some extent with information about CTNNA3 and GABRE gene involvement in branches of diseases associated with leukaemia." (PMID 28303531, 2017).
liver fibrosis (1 paper, 2025). "Our study is the first to demonstrate and confirm that GABRE is upregulated in liver fibrosis samples from both humans and mice." (PMID 40943308, 2025).
myeloma (1 paper, 2023). "miR‐224 is an intronic miRNA located on the GABRE gene, however, our findings suggest that TAZ regulation of miR‐224 in myeloma cells occurs independent of GABRE." (PMID 37539777, 2023).
squamous cell carcinoma (1 paper, 2024). A carcinoma arising from squamous epithelial cells. "All squamous cell carcinoma tumors express a distinct set of GABR genes that are not expressed in normal tissue, including GABRE and GABRA3, while adenocarcinomas show a distinct gene expression signature for a subset of patients or, otherwise, the expression of GABR genes broadly." (PMID 39335139, 2024).
cancer (12 papers, 2013 to 2025). A tumor composed of atypical neoplastic, often pleomorphic cells that invade other tissues. "GABRE activation has the potential to sensitize cancer cells to radiation, chemotherapeutic agents and immune checkpoint inhibitors." (PMID 38951817, 2024). "Few studies have reported that miR‐224 correlates with the expression of GABRE in cancer." (PMID 37539777, 2023). "Expression of GABRG3, GABRQ, GABRE, and GABRR2 is correlated with inhibition of growth phenotypes in cell lines and with favorable patient outcomes (Broad Institute of MIT & Harvard, firebrowse.org), while expression of other transcripts (GABRB2, GABRP) is associated with cancer progression." (PMID 33187258, 2020). "Throughout cancer staging, TCGA database showed consistent reduction in expression levels of GABRA2, GABRE, GABRG1 and GABRP by up to 32.7%, 18.7%, 15.4% and 5.9%, respectively." (PMID 40583063, 2025). "The genetic location of miRNA-224 is within a 200 kb region of Xq28 in close proximity to miR-452 within the GABRE gene and is flanked by the MAGEA4 and MAGEA5 cancer antigens." (PMID 24817781, 2014).
tumor (4 papers, 2019 to 2025). "We found, both in cases and controls, that neither the age at prostate biopsy nor the time interval between two negative biopsies were associated with methylation of GSTP1, APC, C1orf114, GABRE, PITX2, or LINE-1 in non-tumor prostate tissue." (PMID 31666119, 2019).
infection (1 paper, 2022). The state of being infected such as from the introduction of a foreign agent such as serum, vaccine, antigenic substance or organism. "Furthermore, we found that GABRD, GABRB3, GABRE, and GABRQ, which play important roles in neuron cell growth and migration, are significantly downregulated after infection." (PMID 36147849, 2022).
neurological diseases (1 paper, 2025). "Existing research mainly focuses on the role of GABRE in neurological diseases." (PMID 40943308, 2025).
GABRE also shares sentences with these, for which no sentence is quoted: schizophrenia (3 papers); autism (2); adenocarcinoma (1); adult-onset Still disease (1); Anxiety (1); autoimmune liver diseases (1); bipolar disorder (1); cervical cancer (1); Cognitive impairment (1); colorectal cancer (1); focal epilepsy (1); Hypertension (1); Hypsarrhythmia (1); insomnia (1); Intellectual disability (1); keratosis (1); liver diseases (1); lung adenocarcinoma (1); lung carcinoma (1); major depressive disorder (1); medulloblastoma (1); metabolic disorder (1); metastasis (1); ovarian carcinoma (1); personality disorder (1); primary biliary cholangitis (1); pulmonary disorder (1); retinitis pigmentosa (1).